KDM1A (lysine demethylase 1A)
Diseases named in the same sentence as KDM1A in open-access papers (continued):
Sharing a sentence is not in itself a finding about the gene and the disease.
cancer (continued). "Analysis of proteomic data from 159 pairs of HCC tumor and normal tissues showed that KDM1A protein level was increased in cancer compared with normal tissue." (PMID 35970393, 2022). "KDM1A (lysine demethylase 1A), overexpressed in multiple cancer types, is a lysine demethylase that targets both histone and nonhistone proteins." (PMID 35970393, 2022). "Lysine-specific demethylase 1 (LSD1, also known as KDM1A) is an attractive agent for treatment of cancer." (PMID 34491469, 2021). "Multiple studies showed that KDM1A expression is high in various cancers and plays an important role in different cancer-related processes." (PMID 34925656, 2021). "KDM1A plays a pivotal role in various cancer-related physiological processes, such as maintenance of stemness, regulation of hypoxia, epithelial-to-mesenchymal transition (EMT), and escape of immune surveillance." (PMID 34925656, 2021). "KDM1A was highly expressed in 17 types of total 33 cancers, while it expressed low levels in only 4 cancers." (PMID 34925656, 2021). "KDM1A correlated with immunosuppressive tumor microenvironment via various approaches based on pan-cancer analysis." (PMID 34925656, 2021). "Evidence has shown that the dysregulation of KDM1A plays an important role in tumorigenesis in several cancers, including HCC." (PMID 34307695, 2021). "KDM1A is reported as an oncoprotein with upregulated expression detected in cancers, including hepatocellular carcinoma and colorectal cancer." (PMID 34350095, 2021). "HDM inhibitor anti-cancer drugs have been developed that target the HDMs lysine demethylase 1A (LSD1/KMD1A) and 5B (KDM5B) as well as JmjC domain-containing proteins." (PMID 33391954, 2021). "In this study, we performed pan-cancer analysis by using the TCGA project and GTEx databases to systematically characterize the role of KDM1A across various cancer types." (PMID 34925656, 2021). "KDM1A plays critical roles as an important regulator of various aspects of cancer, such as oncogenes, which promote cancer growth, progression and metastasis." (PMID 33799951, 2021). "As the first identified histone demethylase, there are more and more reports have pointed out that KDM1A is a potential drug target for the treatment of cancers." (PMID 33935733, 2021). "KDM1A, lysine-specific histone demethylase, has been reported to involve in the regulation of cancer stem cells." (PMID 34601503, 2021). "Our group and Shi's group have proved inhibition of KDM1A can convert tumors from “cold” to “hot” via regulating the tumor immunogenicity and suppose KDM1A as a target to enhance the efficacy of immunotherapy on poor immunogenic cancers." (PMID 34925656, 2021). "The expression of KDM1A has been found upregulated and correlated with poor prognosis in various cancer types." (PMID 34925656, 2021). "High KDM1A expression was related to upregulated CTA expression, which is associated with cancer antigens in various types of malignancies." (PMID 33799951, 2021). "KDM1A was negatively correlated with Th1 cells and B memory cells but positively correlated with Th2 cells in most cancer types." (PMID 34925656, 2021). "KDM1A is a well-known histone demethylase and an emerging option for the therapeutic treatment of various cancers." (PMID 34350095, 2021). "KDM1A is overexpressed in many cancers and removes lysine methylation on histones that keeps the DNA firmly packed to selectively activate or repress gene activity, depending on the specific lysine target." (PMID 34771652, 2021). "It has been shown to be overexpressed in diverse cancers and contributes to cancer development and progress as an oncogene, thus, inhibition of KDM1A pharmacologically can suppress the proliferation and migration of diverse cancer cells." (PMID 33935733, 2021). "Our comprehensive pan-cancer analysis illustrates the role of KDM1A as an oncogene and predictor of worse survival in most tumor types." (PMID 34925656, 2021).
cancer (continued). "To investigate the DNA methylation of KDM1A, we explore the data of KDM1A DNA methylation of different cancer types in the TCGA project." (PMID 34925656, 2021). "Several reports have implied that PD-L1 expression is connected with mitochondrial function to some extent in cancers, and KDM1A injures mitochondrial function in cancers." (PMID 34307695, 2021). "Several articles have reported that the biological behaviour of KDM1A has a strong correlation with various types of cancers." (PMID 32762026, 2020). "Evidence on the existence of KDM1A first came in 2004, and subsequent studies have demonstrated its involvement with cancer and tumorigenesis." (PMID 33029224, 2020). "Expression of LINC00518 was evaluated, together with CDH1 and VEGFA, two known targets of KDM1A in other cancer models." (PMID 33371395, 2020). "As in cancer cells, KDM1A binds to AR and ESR1 in trophoblast cells, and therefore is thought to play a role in regulating AR and ESR1 signaling in the placenta." (PMID 33029224, 2020). "The demethylase 1 (LSD1/KDM1A) lysine-specific demethylase 1 is an epigenetic enzyme whose overexpression is correlated with poor prognosis in a variety of cancers and has been proposed as therapeutic target." (PMID 30866496, 2019). "Taken together, our data clearly indicated that targeting the KDM1A would rewire the Warburg effect and inhibit cancer cell proliferation, by regulating the key enzyme HK2 expression." (PMID 30568590, 2018). "Lysine-specific demethylase 1 (LSD1/KDM1A) has been proposed as an oncogene whose overexpression has been positively correlated with the malignancy of many cancer types, including prostate [14••, 82], promoting carcinogenesis by multiple mechanisms." (PMID 29888169, 2018). "Several studies showed that various cancers with higher KDM1A expression correction, have high cell proliferation rates." (PMID 30568590, 2018). "Here, we report that autophagy is regulated by the lysine-specific demethylase LSD1/KDM1A, an epigenetic marker whose overexpression is a feature of malignant neoplasia with an instrumental role in cancer development." (PMID 28783174, 2017). "In summary, the effect of KDM1A knockdown in the tested cancer cell lines differs from that observed in ES cells in that it does not alter either the levels of these DNMTs, those of the corresponding mRNAs or DNMT methylation." (PMID 27449289, 2016). "Kaplan–Meier survival curves based on TCGA data support an OLIG2 and KDM1A (AOF2) concerted involvement in cancer development." (PMID 27447975, 2016). "Here, we show that KDM1A promotes cancer metastasis in NSCLC cells by repressing TIMP3 (tissue inhibitor of metalloproteinase 3) expression." (PMID 27058897, 2016). "KDM1A is a histone demethylase specific for H3K4me2/me1 demethylation, and has been found to be overexpressed in many cancers, including non-small cell lung cancer (NSCLC)." (PMID 27058897, 2016). "In the present study, we have explored for the first time the interplay between KDM1A and DNMTs in cancer cells." (PMID 27449289, 2016). "KDM1A is reported to be oncogenic and/or overexpressed in cancers including leukaemias and solid tumours." (PMID 24859458, 2014). "High expression of KDM1A in various cancers, including colorectal cancer, prostate cancer, and neuroblastomas is associated with increased cancer recurrence and poor clinical outcome." (PMID 24808866, 2014). "Since the KDM1A catalytic domain shares homology with neural MAOs, pharmacological inhibitors developed as anti-depressive agents have been employed to target cancer cells." (PMID 22867098, 2012).
cancer (continued). "By exploiting commercially available pharmacological inhibitors, we demonstrate that in AR-positive CRPC cell lines, combinatory inhibition of KDM1A and KDM7A leads to a loss of AR and the AR-driven transcriptome, which in turn attenuates cancer-promoting cell phenotypes." (PMID 41870972, 2026). "However, it is encouraging that clinical trials are already underway exploring the efficacy and safety of HDM inhibitors (mainly KDM1A) in other cancer types." (PMID 40699666, 2025). "Therefore, many pharmacological inhibitors of KDM1A have been developed and shown to inhibit tumor cell proliferation, invasion and migration and are being tested as candidates for cancer therapy." (PMID 40600050, 2025). "Nevertheless, additional studies using nematodes and other animal models are warranted to further decipher the function of KDM1A and to experimentally confirm the role and other less‐explored dual‐purpose targets proposed by our study in both cancers and aging." (PMID 37888486, 2023). "KDM1A also reported to promote tumorigenesis in many cancers." (PMID 36941992, 2023). "Lysine-specific demethylase 1 (LSD1; also known as KDM1A, AOF2; encoded by KDM1A in humans) is a promising target that may be exploited for molecular-based anti-cancer therapies." (PMID 37973845, 2023). "KDM1A was expressed in 19/41 cancers (46.3%) and its expression did not significantly associate with tumor stage (chi-square test; p = 0.644)." (PMID 37385999, 2023). "Interestingly, SMOX has considerable sequence homology to KDM1A, which facilitates the design of dual inhibitors for cancer therapy." (PMID 37046703, 2023). "KDM1A has already been proven to be involved in multiple biological processes of cancer progression, including proliferation 19, epithelial-mesenchymal transformation 20, 21, senescence 22, the maintenance of stem cell pluripotency 23, 24 and multidrug resistance." (PMID 35198054, 2022). "Arborinine was reported to inhibit KDM1A activity in other cancers." (PMID 36185617, 2022). "KDM1A also plays a critical role in BC chemoresistance by maintaining a pool of cancer stem cells." (PMID 35454810, 2022). "For these reasons, the recent entry of KDM1A pharmaco-inhibitors into cancer clinical trials herald a new step in the translation of innovative epigenetic therapies to the clinic, even though some of the trials were terminated due to no beneficial effects in the cancer types treated." (PMID 36263323, 2022). "KDM1A plays versatile roles in physiology and pathophysiology including cancer." (PMID 35970393, 2022). "TCP (Tranylcypromine) was the first identified KDM1A inhibitor that could suppress various cancers and most of the present KDM1A inhibitors are synthesized and modified based on TCP." (PMID 35198054, 2022). "The cancer cases were dichotomized into high and low groups according to KDM1A expression." (PMID 34925656, 2021). "We further explored the transcription levels of KDM1A in cancer using the Oncomine database." (PMID 34925656, 2021). "High KDM1A expression was associated with aggressive clinical outcomes, such as lymph node involvement, high histological grade, HER2 positivity and lymphatic invasion, which can be found in studies of other cancers." (PMID 33799951, 2021). "Considerable studies have highlighted the pivotal role of KDM1A in several cellular processes of normal and cancer cells such as stemness maintaining, differentiation, cell migration, epithelial-to-mesenchymal transition, autophagy, senescence, neurodegenerative diseases, and metabolism." (PMID 34925656, 2021). "These indicated that KDM1A is a potential prognostic biomarker in several cancers." (PMID 34925656, 2021). "However, none of them has entered into market, so, more effective and specific KDM1A inhibitors for therapeutic intervention in various cancers are still needed to be developed." (PMID 33935733, 2021).
cancer (continued). "Additionally, KDM1A in most cancer types was negatively correlated with Th1 cell infiltration and positively correlated with Th2 cells." (PMID 34925656, 2021). "Considering the significant influence of miRNAs on cancer progression, we started to investigate whether there was a miRNA regulating PD-L1 expression by binding to KDM1A." (PMID 34307695, 2021). "It suggested that microbial metabolites may impact the KDM1A level in cancer cells to regulate tumor progression, which needs to be proved via experimental evidence." (PMID 34925656, 2021). "Although increasing evidence supposes the association between KDM1A and cancers, no systematic multi-omics analysis of KDM1A is available." (PMID 34925656, 2021). "An increasing number of studies have revealed the importance of KDM1A in cancer." (PMID 34307695, 2021). "In this study, we used pan-cancer analysis to systematically characterize the roles of KDM1A." (PMID 34925656, 2021). "However, a pan-cancer analysis of KDM1A was still urgently needed to reveal its relationship with cancer from the overall perspective." (PMID 34925656, 2021). "Interestingly, in most cancer types, KDM1A was negatively correlated with CD4+ Th1 cells and positively correlated with CD4+ Th2 cells." (PMID 34925656, 2021). "Therefore, KDM1A is a promising drug target in many cancers, and it is crucial to find effective KDM1A inhibitors, while none of them has entered into market." (PMID 33935733, 2021). "On the one hand, KDM1A plays a role as a transcription cofactor in cancer progression." (PMID 34307695, 2021). "In these cancer cells, KDM1A generally plays a positive role for their growth." (PMID 33987474, 2020). "Some studies have suggested that inhibiting the chemical activity of KDM1A may be a candidate method for cancer treatment." (PMID 32762026, 2020). "The lysine-specific histone demethylase 1A (LSD1) also known as lysine (K)-specific demethylase 1A (KDM1A) is a central epigenetic regulator of metabolic reprogramming in obesity-associated diseases, neurological disorders, and cancer." (PMID 31331073, 2019). "KDM1A has been characterized as a potential oncogene and a therapeutic target in various cancers." (PMID 30568590, 2018). "In this review, we discuss the microenvironment of KDM1A in cancer progression that enables this protein to activate or repress target gene expression, thus making it an important epigenetic modifier that regulates the growth and differentiation potential of cells." (PMID 29921310, 2018). "For this reason, the cancer metabolic reprogramming driven by KDM1A, has attracted much attention." (PMID 30568590, 2018). "It is therefore interesting to test whether targeting KDM1A, would block metabolic reprogramming in cancer cells driven by KDM1A." (PMID 30568590, 2018). "Many cancer cells are reported to have significantly increased KDM1A expression levels." (PMID 27449289, 2016). "We then investigated the impact of KDM1A depletion on the DNA methylation level in cancer cells." (PMID 27449289, 2016). "In this work, we present evidence that KDM1A interacts with DNMTs in cancer cells." (PMID 27449289, 2016). "We provide evidence that in cancer cells, KDM1A interacts with both DNMT1 and DNMT3B." (PMID 27449289, 2016). "In the future, it should be interesting to test whether combining DNMT inhibitors with KDM1A inhibitors can be beneficial to patients in cancer treatment." (PMID 27449289, 2016). "Overexpression of KDM1A contributes to tumorigenesis in many types of cancer." (PMID 27058897, 2016). "Our results thus indicate that KDM1A acts differently in cancer cells than in ES cells." (PMID 27449289, 2016). "Together, our findings propose a mechanistic link between KDM1A and DNA methyltransferases in cancer cells and suggest that the KDM1A/DNMT1 interaction may play a role during replication." (PMID 27449289, 2016).
cancer (continued). "Known, validated targets for miR137 include the cell cycle regulator Cdc42, estrogen related receptor ERRα/NR3B1, p160 nuclear receptor coactivators and the lysine specific demethylase 1 (KDM1A, LSD1), a transcriptional coregulator which is over-expressed in many cancers [14 and references therein]." (PMID 26461474, 2015). "NCOA2, KDM1A, KDM4A, KDM5B and MED1 are AR coregulators implicated in prostate and other cancers." (PMID 26461474, 2015). "Notably, high KDM1A activity is present in many cancer types, including BCa45,46." (PMID 37945904, 2023). "Epigenetic targeting is an area of growing interest in cancer treatment and KDM1A overexpression is usually associated with poor prognosis, stemness maintenance, epithelial-to-mesenchymal transition (EMT), and escape of immune surveillance in a variety of cancers." (PMID 37385999, 2023). "In addition, KDM1A was significantly upregulated in 10 of 11 cancer types." (PMID 37888486, 2023). "Thus, we comprehensively investigated the expression and efficacy of KDM1A on a total of 33 different cancer types in TCGA, GTEx, and CPTAC databases from the following aspects including gene expression, mutations, protein phosphorylation, DNA methylation, and tumor-infiltrating immune." (PMID 34925656, 2021). "However, little is known about the relationship between KDM1A and immune checkpoints in cancer." (PMID 34307695, 2021). "Nevertheless, the precise contribution of KDM1A to cancer metabolism remains unclear." (PMID 30568590, 2018). "The connection between DNMT1 and KDM1A could be of clinical value, for instance in cancer therapy." (PMID 27449289, 2016). "KDM1A specifically interacts with the androgen receptor or with large chromatin-modifying corepressor complexes such as the Co-REST complex, suggesting that high-level KDM1A expression might already affect genes during the embryonal development of potential cancer progenitor cells." (PMID 24252778, 2013). "Lysine demethylase 1A (KDM1A), a histone demethylase that removes methyl groups from histones H3K4 and H3K9, is overexpressed in multiple cancers, including ccRCC, where it drives tumorigenesis." (PMID 40426910, 2025). "Specifically, capsaicin acts as an inhibitor of the Lysine Specific Demethylase 1A (KDM1A/LSD1), which is overexpressed in different kinds of cancer." (PMID 40510497, 2025). "KDM1A can interact with and demethylate FKBP8, enhancing its ability to stabilize BCL2, which promotes cancer cell growth and the development of acquired drug resistance." (PMID 40164592, 2025). "RT-qPCR analysis confirmed that KDM1A and STAT3 expression levels were substantially higher in cancer cells (HSC3 and CAL27) than in normal epithelial cells." (PMID 40246812, 2025). "The results indicated that KDM1A and KDM5A significantly interact with HDAC1/2, which plays a critical role in cancer by regulating gene expression through histone deacetylation, thereby influencing cell proliferation, apoptosis, and metastasis." (PMID 39239542, 2024). "Another promising target is represented by histone demethylases: in particular, lysine-specific demethylase 1 (LSD1/KDM1A), the first discovered histone lysine demethylase, can disrupt the molecular changes driving the epigenetic plasticity of cancer cells." (PMID 39519290, 2024). "Subsequently, multi-omics techniques were used to characterize the cancer hallmarks and spatial immune properties in ESCC tissues with low or high KDM1A expression." (PMID 39638799, 2024). "The first reported lysine demethylase (KDM) enzyme specific to H3K4 and H3K9 residues, LSD1 (KDM1A), is a classic oncogene and is overexpressed in many types of cancer." (PMID 39308891, 2024). "LSD1/KDM1A is overexpressed in many proliferative diseases, including cancers, highlighting its use as a potential target in oncology." (PMID 38612726, 2024).